MTOR (mechanistic target of rapamycin kinase)
Diseases named in the same sentence as MTOR in open-access papers (continued):
Sharing a sentence is not in itself a finding about the gene and the disease.
autoimmune disease (continued). "Meanwhile, dual mTOR kinase inhibitors are being tested in clinical trials to treat various types of human cancer, to prevent organ rejection and to control autoimmune diseases." (PMID 33013932, 2020). "Dysregulation of mTOR signaling has been reported in various autoimmune diseases and transplantation settings and can be targeted by immunosuppressive drugs like sirolimus and everolimus." (PMID 31105702, 2019). "While Bregs expanded with pentanoate suppressed the autoimmune disease in the CNS, the pretreatment of these cells with mTOR/p38 MAPK inhibitors resulted in markedly reduced ability to protect mice from EAE." (PMID 30770822, 2019). "Recent studies suggested that mTOR activity plays a critical role in B cells during autoimmune diseases." (PMID 29915588, 2018). "Immunosuppressive drug rapamycin (RPM), targeting on the key cellular metabolism molecule mTOR, is currently used in clinics to treat patients with allo-grafts, autoimmune diseases and tumors." (PMID 26833095, 2016). "The PI3K/Akt/mTOR signaling pathway was essential to cellular proliferation and growth signaling and was correlated with autoimmune diseases due to its activation in lymphocytes that developed features of systemic autoimmunity." (PMID 26560501, 2015). "Therefore, our narrative review aimed to summarize and discuss recent advances in the knowledge of the activation of mTOR signaling in macrophages, with a special focus on autoimmune disorders and the possibility of mTOR control by microRNAs." (PMID 40806725, 2025). "Notably, mTOR-targeted immunotherapy has demonstrated remarkable success in managing autoimmune disorders and malignancies, and has been gradually transitioned to clinical practice." (PMID 40933998, 2025). "Moreover, mTOR plays a fundamental role in protein transcription and translation involved in many inflammatory and autoimmune diseases." (PMID 38711460, 2024). "Indeed, targeting glycolysis via mTOR ameliorates symptoms of autoimmune disorders, for example, improving disease markers such as the SLE activity index in both humans and mice models." (PMID 38500390, 2024). "Furthermore, mTOR inhibitors have demonstrated efficacy in the treatment of psoriasis and other autoimmune diseases, highlighting the importance of this pathway in the pathogenesis of PsA." (PMID 38426052, 2024). "Inhibition of mTOR can induce immunosuppression in autoimmune diseases and organ transplantation." (PMID 36890410, 2023). "mTOR inhibitor is a promising therapeutic target for autoimmune diseases." (PMID 38164133, 2023). "A study found that rapamycin decreased macrophage secretion of IL-18 and IL-1β by reducing caspase-1 activation, indicating that inhibition of mTOR may be advantageous for patients with inherited autoimmune diseases." (PMID 36595872, 2022). "In addition to cancer, the mTOR pathway plays critical roles in the pathogenesis of autoimmune diseases and infectious diseases." (PMID 34895234, 2021). "Similar to mTOR signaling, the JAK/STAT pathway has been implicated in the pathogenesis of autoimmune states and irAEs, and the inhibition of JAK/STAT signaling has led to remarkable remissions in the setting of autoimmune disorders." (PMID 34899357, 2021). "This may suggest new therapeutic and preventive strategies for autoimmune diseases by targeting the specific mechanisms of trained immunity, such as glycolysis and the mTOR signaling pathway." (PMID 33082707, 2020). "Activation of the mTOR pathway in autoimmune diseases suggests that SRL might be a useful agent for treating ITP." (PMID 32296709, 2020). "More studies are needed to focus on the relationship of CD8 T cell and mTOR and how the regulation of CD8 T cell by mTOR may be exerted through epigenetic mechanisms in autoimmune diseases." (PMID 31057561, 2019). "Indeed, available mTOR inhibitors showed therapeutic potential for autoimmune diseases including SS." (PMID 31164166, 2019).
autoimmune disease (continued). "Besides, the mTOR-dependent autophagy is impaired in patients with ulcerative colitis (UC), implicating mTOR also as a therapeutic target for autoimmune diseases." (PMID 31547370, 2019). "SLC15A4 also regulates mTOR-dependent inflammatory responses in B cells, and deficient SLC15A4 may contribute to the pathogenesis of autoimmune disease." (PMID 30069489, 2018). "Since we have shown here that the cytokine-induced pathway for IFN-γ production is blocked by rapamycin, mTOR may be a therapeutic target in the treatment of autoimmune diseases characterized by IFN-γ overexpression." (PMID 21572994, 2011). "However, some basic studies have shown that mTOR regulates the homeostasis of immune cells in an interactive manner, thus, targeting mTOR in immune cells may destroy the immune tolerance and lead to autoimmune diseases." (PMID 32041519, 2020). "Notably, mTOR-driven autophagy is also an important mechanism in autoimmune diseases." (PMID 29915588, 2018). "Dysregulation of the mTOR and AMPK pathways leads to immune imbalance in various autoimmune diseases and metabolic disorders." (PMID 39996755, 2025). "Taken together, these data show that DOCK8 can regulate the levels of glycolysis and oxidative phosphorylation by stabilizing the mTOR/HIF‐1α signaling pathway, thereby inhibiting the abnormal differentiation of Th17 cell and autoimmune disease development." (PMID 39329018, 2024). "Recent studies had revealed that AIM2 enhanced the stability of Treg cells by attenuating AKT phosphorylation, mTOR and MYC signaling, and glycolysis, while promoting lipid oxidative phosphorylation, thereby ameliorating autoimmune diseases." (PMID 39600708, 2024). "Additional focus will be placed on the main classes of immune inhibitor therapy utilized in transplant patients and in autoimmune disease including TNF-alpha, Calcineurin, mTOR, purine synthesis antagonists and IMPDH inhibitors." (PMID 36672607, 2022). "Nevertheless, while some immuno-modulatory drugs of the glycolysis/mTOR pathway, such as MMF, methotrexate, and DMF, are used in some autoimmune diseases, many potent glycolysis-inhibitory molecules are still in the pre-clinical phase of study." (PMID 35626700, 2022). "It has been found that mTOR signaling is not only deregulated in cancer but also in different pathological conditions and the mTOR pathway is critical to the pathogenesis of HIV-related malignancies and different autoimmune diseases." (PMID 32806551, 2020). "Therefore, the interactions and balance between the AMPK, mTOR and ULK1 proteins are pivotal in regulating autoimmune diseases." (PMID 40599805, 2025). "In autoimmune diseases, the Slc7a5-mTORC1 pathway may offer a new therapeutic approach, LAT1 deletion or inhibition effectively regulates IL-23 and IL-1β-induced PI3K/AKT/mTOR activation." (PMID 41385507, 2025). "These compounds effectively intervene in the overactive inflammation and immune responses characteristic of rheumatic and autoimmune diseases by modulating various signaling pathways, including the TNF, Toll-like, IL-6, RANKL, MAPK, PI3K/AKT/mTOR, JAK/STAT, and NRF2/GPX4 pathways." (PMID 39524446, 2024). "Furthermore, consistent with the AKT1/mTOR pathway regulating IL-17 in various autoimmune diseases, the miR-let-7d-3p knockout increased IL-17 levels via the AKT1/mTOR pathway, and co-overexpressing AKT1 with miR-let-7d-3p recovered IL-17 expression." (PMID 39062113, 2024). "exhibits anti-inflammatory properties and regulates immune cells and various signaling pathways (e.g., the G protein-coupled receptor (GPCR) pathway, the MAPK/NF-κB pathway, the PI3K/Akt/mTOR pathway, and transforming growth factor beta (TGF-β)/Smad signaling, amongst others) in autoimmune diseases." (PMID 35186100, 2022). "In addition, CD8 T cells and mTOR are new concepts and targets for SLE and other autoimmune diseases." (PMID 31057561, 2019).
autoimmune disease (continued). "Taken together, we speculate that high levels of mTOR activation in T cells from ANA-positive patients contribute to autoantibody production by expanding effector T cells and PD1+ICOS+ TFH, which may eventually promote future development of autoimmune disease." (PMID 36311777, 2022). "Overall, contemporary research reviewed indicates that mTOR signaling activation is a positive regulator for the differentiation of CD4+ effector T cells and a negative regulator for Treg differentiation, and dysregulated mTOR signaling is involved in a number of autoimmune diseases." (PMID 35055151, 2022). "The mechanism by which metformin treats these autoimmune diseases is multifaceted, involving the reconstitution of immune system homeostasis, regulation of 5’-AMP-activated protein kinase (AMPK)- mammalian target of rapamycin (mTOR) signaling pathways and improving gut microbe metabolism." (PMID 34124070, 2021). "However, future studies are warranted to investigate the pathogenic and protective role of CD8+ T cells and how the regulation of CD8+ T cell by mTOR may be exerted through epigenetic mechanisms in SLE and other autoimmune diseases." (PMID 31057561, 2019).
neuroendocrine tumors (99 papers, 2012 to 2025). "Mutations associated with the mTOR pathway have been detected in 18% of neuroendocrine tumors." (PMID 36428761, 2022). "Although both somatic TSC1 mutation and mTOR mutations have been reported in exceptional responders, these alterations are relatively rare in tumor types such as hormone–receptor positive breast cancer and neuroendocrine tumors, where rapalogs are commonly used." (PMID 25944619, 2015). "mTOR hyperactivation has frequently been detected in neuroendocrine tumors but also in poorly differentiated NECs." (PMID 39199391, 2024). "Hyperactivation and/or upregulation of the mTOR signaling pathway are reported in neuroendocrine tumors, including PitNETs." (PMID 39224564, 2024). "Everolimus is an oral inhibitor of the mammalian target of rapamycin (mTOR) with anti-cancer activity in multiple tumor types, including well-differentiated neuroendocrine neoplasms, named neuroendocrine tumors (NETs)." (PMID 39594728, 2024). "Everolimus acts directly on mTOR and is approved for lung, gastrointestinal, neuroendocrine tumors, and advanced renal carcinoma while selumetinib directly inhibits ERK, and its application is approved for neurofibromas." (PMID 37894790, 2023). "Everolimus, an mTOR inhibitor regulates neuroendocrine tumor cell proliferation and has been efficacious in increasing progression-free survival in various trials." (PMID 37568540, 2023). "Neuroendocrine tumors (NETs) are rare neoplasms that often present upregulation of the mammalian rapamycin targeting pathway (mTOR) with consequent uncontrolled growth and proliferation." (PMID 35805003, 2022). "Octreotide and mTOR inhibitor treatment suppressed cell proliferation by inhibiting AKT-mTOR-p70S6K pathway activation in neuroendocrine tumor cell lines." (PMID 34898367, 2022). "Neuroendocrine tumors (NETs) are rare neoplasms frequently characterized by an upregulation of the mammalian rapamycin targeting (mTOR) pathway resulting in uncontrolled cell proliferation." (PMID 35805003, 2022). "In this study, we examined the effects of chloroquine alone or in combination with mTOR inhibitors on lung neuroendocrine tumor models (cell lines and mice)." (PMID 34944946, 2021). "Everolimus (Eve), which is a mammalian target of Rapamicin (mTOR) inhibitor, is part of the therapeutic armamentarium of neuroendocrine tumors (NETs)." (PMID 32397669, 2020). "This review aims to highlight the role of the PI3K/Akt/mTOR pathway in the development of a neuroendocrine tumor and its potential as a therapeutic target providing a biomolecular overview and reporting results from clinical trials." (PMID 33304317, 2020). "A growing body of evidence shows the link between activated mTOR signaling and tumor formation, including neuroendocrine tumors." (PMID 32373532, 2020). "This review aims to highlight the role of the PI3K/Akt/mTOR pathway in the development of neuroendocrine tumors and further specify its potential as a therapeutic target in advanced stages." (PMID 33304317, 2020). "Overexpression of mTOR has been demonstrated in poorly differentiated NENs, but the expression rate decreased in well-differentiated neuroendocrine tumors and carcinomas (67 vs. 27% of analyzed tissues by IHC)." (PMID 33304317, 2020). "Although the inhibition of mTOR is a promising treatment for neuroendocrine tumors, several questions are still open for cell specificity and resistance." (PMID 32373532, 2020). "This situation reflects quite precisely the clinical observation on growth retardation and validates that neuroendocrine tumors are responsive to mTOR inhibition." (PMID 32373532, 2020). "Peptide receptor radionuclide therapy (PRRT) with [177Lu]Lu-DOTA0,TYR3-octreotate ([177Lu]Lu-DOTA-TATE) and the mechanistic target of rapamycin (mTOR) inhibitor everolimus are both approved for the treatment of neuroendocrine tumours (NET)." (PMID 32335736, 2020).
neuroendocrine tumors (continued). "Everolimus is an inhibitor of the mammalian target of rapamycin (mTOR) used as a systemic therapy in lung and gastroenteropancreatic neuroendocrine tumors." (PMID 31540509, 2019). "The aim of this study was therefore to identify miRNAs specifically targeting the mTOR pathway in lung neuroendocrine neoplasms as well as to validate their potential functional role as modulators of mTOR pharmacological inhibition." (PMID 29938004, 2018). "Seven miRNAs were selected and tested in tissue samples from a large series of lung neuroendocrine neoplasms in correlation with mTOR gene expression." (PMID 29938004, 2018). "Archival material should be available for revision according to WHO 2010 neuroendocrine tumor classification and for p-mTOR, SSTR2A, and IGF-1R immunostaining, calculating a quantitative score (QS)." (PMID 29213282, 2017). "The mTOR pathway has been shown to be up-regulated in most gastroenteropancreatic neuroendocrine tumors." (PMID 28423496, 2017). "The mTOR inhibitor everolimus has proven anti-tumoral efficacy in several clinical phase 3 trials in patients with neuroendocrine tumors and is approved for pancreatic, intestinal and pulmonary neuroendocrine tumors." (PMID 28542590, 2017). "The aim of this review is to provide an overview of the role of the mTOR pathway in the pathogenesis of neuroendocrine tumors and to review the role of mTOR inhibitors in the treatment of this disease." (PMID 25092520, 2014). "Everolimus (EVE) is an FDA-approved mTOR inhibitor for the treatment of neuroendocrine tumors." (PMID 39224564, 2024). "The mammalian target of rapamycin (mTOR), an intracellular protein kinase within the phosphoinositide-3 kinase family, is a pivotal component in the cell signalling pathway that contributes to the development of neuroendocrine tumors." (PMID 39022484, 2024). "Notably, mTOR inhibitors have been widely used in the treatment of neuroendocrine tumors (NETs), for example, everolimus has been approved in pancreatic, gastrointestinal and lung NETs62." (PMID 36344509, 2022). "Thus, mTOR inhibition seems to be an adequate therapeutic protocol for testing the role of mTOR in the growth neuroendocrine tumors." (PMID 32373532, 2020). "Neuroendocrine tumors were among the first tumors to be treated with mTOR inhibition." (PMID 32373532, 2020). "The comprehensive immunomonitoring analysis performed in this study provides relevant insight for the rational design of future therapeutic approaches in mRCC and other malignancies such as neuroendocrine tumors, in which mTOR inhibitors are also used as anti-cancer therapeutics." (PMID 30756132, 2019). "The mTOR inhibitor everolimus has shown encouraging results in neuroendocrine tumors." (PMID 26294908, 2015). "Based on the mechanism of action, combining somatostatin analogues (SSAs) with mTOR inhibitors or antiangiogenic agents may provide synergistic effects for the treatment of patients with neuroendocrine tumours (NETs)." (PMID 26138480, 2015). "mTOR inhibitors are increasingly administered for the treatment of neuroendocrine tumors." (PMID 23822543, 2013). "Therapeutic targets for neuroendocrine tumors include phosphatidylinositol-3-kinase (PI3K)/Akt and rapamycin (mTOR), both of which are involved in cell-cycle and growth control pathways in cancer." (PMID 32903471, 2020). "Everolimus, an inhibitor of the mammalian target of rapamycin (mTOR) signaling, was shown to effectively treat advanced PNETs in the RADIENT-3 (RAD001 in Advanced Neuroendocrine Tumors-3) study." (PMID 28730577, 2017). "Furthermore, mTOR, a downstream component of the PI3K/Akt pathway, has also been reported to be dysregulated in neuroendocrine tumors, playing a critical role in tumorigenesis." (PMID 34316328, 2021).
neuroendocrine tumors (continued). "Cross-talk between the PI3K/AKT/mTOR pathway and the MAPK pathway has been described in neuroendocrine neoplasms and other cancer types, and dual inhibition of these pathways has been shown to be more effective in in vitro and in vivo neuroendocrine neoplasm models." (PMID 32512761, 2020). "Biotherapy with somatostatin analogues, the mTOR inhibitor everolimus, the VEGF inhibitor sunitinib, and 177Lu-DOTATATE radionuclide therapy has emerged as evidence-based treatment of advanced G1/G2 neuroendocrine tumors prolonging PFS and/or OS." (PMID 31527438, 2019). "Recently, everolimus, a small molecule mTOR inhibitor, has been approved in the treatment of non-functional metastatic neuroendocrine tumors of the lung or gastrointestinal tract based on the progression-free survival benefit seen in the RADIANT-4 trial." (PMID 29594044, 2018). "In our context, SEMA3F could slow proliferation by reducing the activity of mTOR and MAPK pathways, demonstrated to be up-regulated in several cancer types, including neuroendocrine tumors." (PMID 26447612, 2015). "The mTOR inhibitor everolimus has shown promising results in some but not all neuroendocrine tumors." (PMID 24626055, 2014). "In our study, these results could not be translated to neuroendocrine neoplasms, where the mTOR pathway might play another role in tumorigenesis." (PMID 32631270, 2020).